HOXA5 (homeobox A5)
Diseases named in the same sentence as HOXA5 in open-access papers (continued):
Sharing a sentence is not in itself a finding about the gene and the disease.
adenoma (3 papers, 2019 to 2022). A neoplasm arising from the epithelium. "Expression changes detected by RNA-seq were validated in an expanded set of samples by RT-qPCR for IL10, SOX9, GBX2, and HOXA5, genes with biological functions that may contribute to the reduced progression of hyperplasia to adenoma." (PMID 33632299, 2021). "However, HOXA5 expression has been shown to be progressively downregulated during the adenoma-carcinoma transition in colon tissue, suggesting that HOXA5 protein may function as a tumor suppressor protein." (PMID 31159758, 2019).
diabetes (3 papers, 2021 to 2023). "To test this hypothesis, we adopted bisulfite sequencing and analyzed DNA methylation levels at the HOXA5 promoter, comparatively, in preadipocytes from individuals who were FDR of type 2 diabetics and in those who had no diabetes familiarity." (PMID 35203377, 2022).
Type 2 Diabetes (3 papers, 2022 to 2025). "Altered DNA methylation of the HOXA5 promoter contributed to restricted adipogenesis in the SAT of lean subjects who were FDR of type 2 diabetics and in obese individuals." (PMID 35203377, 2022). "Moreover, individuals with a family history of type 2 diabetes (T2D) and hypertrophic obesity exhibit elevated methylation levels of the HOXA5 gene, which correlates with larger fat cell sizes and a higher BMI." (PMID 40564006, 2025).
adrenocortical carcinoma (2 papers, 2021 to 2023). "Aldo-Keto Reductase Family 1 Member B10 (AKR1B10) and Homeobox A5 (HOXA5) are both down-regulated in adrenocortical carcinoma (ACC), and HOXA5 is predicted to bind to the promoter of AKR1B10." (PMID 34027794, 2021).
and Kabuki syndromes (2 papers, 2022). "CpG sites annotated to the HOXA5 gene have been associated to 33 different traits, with the most frequently reported associations including depressive disorders (46 associations), Kabuki syndrome (33 associations), and inflammatory bowel disease (23 associations)." (PMID 35836279, 2022). "In our previously published disorder-specific DNAm signatures we identified aberrant HOXA5 methylation in individuals with Weaver and Kabuki syndromes." (PMID 35361921, 2022).
cervical squamous cell carcinoma (2 papers, 2020 to 2024). A squamous cell carcinoma arising from the cervical epithelium. "However, Pei and colleagues found that HOXA5 was lowly expressed in cervical squamous cell carcinoma patients with poor differentiation." (PMID 32499530, 2020). "Elevated levels of miR-142-5p in HPV16-integrated cervical epithelial cells directly suppress HOXA5, resulting in increased transcription of SLC7A11, which aids in resistance to ferroptosis and the progression of cervical squamous cell carcinoma (CSCC)." (PMID 39420439, 2024).
CHARGE syndrome (2 papers, 2017 to 2023). CHARGE syndrome is a multiple congenital anomaly syndrome characterized by the variable combination of multiple anomalies, mainly Coloboma; Choanal atresia/stenosis; Cranial nerve dysfunction; Characteristic ear anomalies (known as the major 4 C's). "Notably, the HOXA5 DMR found in the JARID2-neurodevelopmental disorder is also hypomethylated in CHARGE syndrome, which may explain some of the clinical overlap observed between JARID2-neurodevleopmental disorder and CHARGE." (PMID 37762546, 2023).
endometrial cancer (2 papers, 2023 to 2025). Primary or metastatic malignant neoplasm involving the endometrium (mucous membrane that lines the endometrial cavity). "We examined tissue samples from 75 patients with endometrial cancer and found that high HOXA5 expression was linked to increased tumor cell growth, but at the same time it was associated with better overall survival." (PMID 40805172, 2025). "Given its established tumor-suppressive role in several other malignancies, HOXA5 may serve as a valuable complementary marker to enhance molecular risk stratification in endometrial cancer." (PMID 40805172, 2025). "In our study, patients with high HOXA5 expression exhibited better survival outcomes, which contrasts with the previously reported association between high Ki-67 expression and poor prognosis in endometrial cancer." (PMID 40805172, 2025). "Our findings suggest that HOXA5 plays a complex and context-dependent role in endometrial cancer (EC)." (PMID 40805172, 2025).
esophageal squamous cell carcinoma (2 papers, 2019 to 2022). Esophageal squamous cell carcinoma (ESCC) is a type of esophageal carcinoma (EC) that can affect any part of the esophagus, but is usually located in the upper or middle third. "However, other studies have reported that knockdown of Hoxa5 suppressed the esophageal squamous cell carcinoma (ESCC) cell proliferation, which might be partly mediated via interfering with Wnt/β-catenin signaling pathway." (PMID 35883405, 2022).
lymph node metastasis (2 papers, 2017 to 2022). "However, our study found for the first time that methylation of RHOF, CRMP1, BNIP3 and HOXA5 promoters is associated with lymph node metastasis." (PMID 36454866, 2022). "Overall mortality was significantly associated with advanced FIGO stage, lymph node metastasis, lymphovascular invasion, and increased HOXA1, HOXA5, HOXA6, and HOXC11 mRNA expression." (PMID 29137433, 2017). "However, methylation of RHOF, CRMP1, BNIP3 and HOXA5 promoters has not been reported to be associated with lymph node metastasis, and our study is the first to find that methylation of these gene promoters is associated with lymph node metastasis." (PMID 36454866, 2022).
mental disorder (2 papers, 2022 to 2025). A disease that has its basis in the disruption of mental process. "One gene of particular interest is HOXA5, which has previously been associated with organogenesis, lung function in adults and mental disorder phenotypes." (PMID 40349045, 2025). "Notably, HLA genes and HOXA5 have also been associated with mental disorders and the latter may be important in development." (PMID 40349045, 2025).
myelogenous leukemias (2 papers, 2007 to 2019). "Meis1 is known to be coexpressed with homeobox genes, such as HOXA5, 7 and 9 in myelogenous leukemias." (PMID 17615543, 2007).
respiratory failure (2 papers, 2017 to 2025). The significant impairment of gas exchange within the lungs resulting in hypoxia, hypercarbia, or both, to the extent that organ tissue perfusion is severely compromised. "Hoxa5 plays a pivotal role in respiratory system development, as mutations can disrupt the formation of trachea, lung, and diaphragm, leading to respiratory failure and neonatal mortality." (PMID 41044788, 2025). "Spatiotemporal inactivation of Zpr1 gene in motor neurons down-regulates HoxA5 and causes defects in the function of phrenic motor neurons that results in respiratory failure and perinatal lethality in mice." (PMID 28811488, 2017). "The results of this study demonstrate that the low levels of ZPR1 cause down-regulation of HoxA5 that leads to degeneration of phrenic motor neurons and respiratory failure in mice." (PMID 28811488, 2017). "Respiratory distress caused by the low levels of HoxA5 in Zpr1 mutant mice and SMA mice is consistent with finding that HoxA5 deficiency causes degeneration of phrenic motor neurons and respiratory failure in mice." (PMID 28811488, 2017). "In SMA, SMN-deficiency causes deregulation of ZPR1 and HoxA5 that lead to respiratory failure." (PMID 28811488, 2017). "Together, these findings provide insight into the molecular basis of respiratory failure associated with SMA pathogenesis and identify ZPR1 and HoxA5 as potential targets that lay a foundation for developing therapeutic strategies to treat respiratory distress in SMA." (PMID 28811488, 2017).
acute kidney injury (1 paper, 2025). Sudden and sustained deterioration of the kidney function characterized by decreased glomerular filtration rate, increased serum creatinine or oliguria. "Dismantling the proteasome‐mediated turnover of HOXA5 contributes to the prevention of septic acute kidney injury." (PMID 39713961, 2025).
autism (1 paper, 2017). Persistent deficits in social interaction and communication and interaction as well as a markedly restricted repertoire of activity and interest as well as repetitive patterns of behavior. "In this context, several genes downregulated in the brainstem of Hoxa5 cKO mouse at P21, such as Grm4, Cbln1, En2, Camk4, and Cadps2, have been associated to autism traits either in humans or in mouse models." (PMID 29187810, 2017). "Although HOXA5 protein has not been detected in the forebrain-derived territories, which have been mostly investigated in deciphering ASD underlying pathways, recent analysis highlights a role for the cerebellum in the perinatal risks for autism." (PMID 29187810, 2017).
brain tumor (1 paper, 2025). "Studies report that galectin-1 regulates angiogenesis-related genes via RNA binding, while its complex formation with HOXA5 reprograms transcriptional networks in brain tumor stem cells." (PMID 40863614, 2025).
carcinoma of the lip (1 paper, 2022). "HOXA5, HOXB9, HOXC8, HOXC10, and HOXC11 genes were specific to certain sites of the oral cavity whereas HOXA10 was associated with the development of the carcinoma of the lip and oral cavity." (PMID 35710803, 2022).
cholangiocarcinoma (1 paper, 2022). A carcinoma that arises from the intrahepatic biliary tree (intrahepatic cholangiocarcinoma) or from the junction, or adjacent to the junction, of the right and left hepatic ducts (hilar cholangiocarcinoma). "In the present study, we found hypermethylation in the promoters of many HOX genes, particularly for HOXA5, associated with down-regulated HOXA5 expression in cholangiocarcinoma and ECCA cells." (PMID 36167790, 2022). "To understand the expression pattern of HOXA5 in cholangiocarcinoma, we characterized the expression of HOXA5 in cholangiocarcinoma and controlled tissue arrays by IHC." (PMID 36167790, 2022). "However, little is known on whether and how HOXA5 can regulate the malignant behaviors of cholangiocarcinoma." (PMID 36167790, 2022). "The levels of HOXA5 promoter methylation in cholangiocarcinoma tissues were significantly higher than those in non-tumor tissues." (PMID 36167790, 2022). "However, there is no information on whether HOXA5 can regulate MXD1 expression and its downstream signaling in cholangiocarcinoma." (PMID 36167790, 2022).
chordoma (1 paper, 2023). Chordomas are rare malignant tumors arising from embryonic remnants of the notochord in axial skeleton. "Chordoma-specific DMRs were also found in location of homeobox domain genes (e.g. DMRs in HOXA4, HOXA5, HOXD3, HOXD4 MNX1, and NFIX) especially on chromosome 2 at HOXD cluster." (PMID 37434245, 2023).
chronic obstructive pulmonary disease (1 paper, 2016). A chronic and progressive lung disorder characterized by the loss of elasticity of the bronchial tree and the air sacs, destruction of the air sacs wall, thickening of the bronchial wall, and mucous accumulation in the bronchial tree. "Similarly, an increased Notch signaling activity occurs in the lung airway epithelium from Hoxa5−/− mice and in areas of goblet cell metaplasia in patients suffering from chronic obstructive pulmonary disease (COPD)." (PMID 29615582, 2016).
colorectal tumors (1 paper, 2016). "The decreased HOXA5 expression in colorectal tumors correlates with high levels of nuclear β-catenin, a hallmark of Wnt signaling activity." (PMID 29615582, 2016). "Moreover, HOXA5 overexpression in colorectal tumors following a retinoid treatment suppresses the self-renewal capacity of cancer stem cells by inhibiting Wnt signaling." (PMID 29615582, 2016).
COVID-19 (1 paper, 2022). A disease caused by infection with severe acute respiratory syndrome coronavirus 2. "Only two gene sets had significant p values when multiple testing was considered, these were the Hoxa5 gene set mentioned previously and a COVID-19-related gene set." (PMID 36344500, 2022).
dysplasia (1 paper, 2015). A usually neoplastic transformation of the cell, associated with altered architectural tissue patterns. "Moreover, direct topical application of a HoxA5 transgene to neoplastic skin in K14-HPV16 mice resulted in a similar impaired progression to high grade dysplasia accompanied by a similar reduction in angiogenesis, mast cell recruitment and concomitant changes in gene expression." (PMID 25821967, 2015). "Thus activation of EC HoxA5 in HPV16/HoxA5 mice was reflected by reduced angiogenesis and progression to dysplasia." (PMID 25821967, 2015).
emphysema (1 paper, 2025). "Finally, HOXA5 showed elevated expression in lung tissue, consistent with its essential function in respiratory tract morphogenesis; HOXA5 knockout mice exhibit severe postnatal lung defects including alveolar damage and emphysema." (PMID 41515917, 2025).
endometrioid adenocarcinoma (1 paper, 2023). An adenocarcinoma characterized by the presence of malignant glandular epithelial cells resembling endometrial cells. "This study aimed to determine the association between HOXA5 gene expression and the prognosis of endometrioid adenocarcinoma, a subtype of EC (EAEC)." (PMID 37834206, 2023). "In this study, we investigated the relationship between HOXA5 gene expression and EC prognosis, focusing on the endometrioid adenocarcinoma subtype of EC (EAEC)." (PMID 37834206, 2023).
endometriosis (1 paper, 2021). The growth of functional endometrial tissue in anatomic sites outside the uterine body. "Our study identified two major downstream targets, HOXD10 and HOXA5, regulated by HOTAIR in advanced endometriosis and the associated ovarian clear cancer cells." (PMID 33667269, 2021). "Our data confirm the molecular link between HOTAIR and those homeobox proteins, suggesting the involvement of HOXD10 and HOXA5 in endometriosis progression." (PMID 33667269, 2021). "The most responsive downstream targets, genes at the HOXA and HOXD loci, that associated with elevated HOTAIR in severe endometriosis were HOXD10 and HOXA5." (PMID 33667269, 2021). "Downstream screening using data from clinical and cell-based studies revealed HOXD10 and HOXA5 to be the key regulators for HOTAIR to promote endometriosis progression." (PMID 33667269, 2021). "In addition, our data indicated that functional axes of HOTAIR/HOXD10 and HOTAIR/HOXA5 may play potent roles in regulating endometriosis progression." (PMID 33667269, 2021). "Data mining further revealed higher mRNA HOTAIR levels in the endometria of patients with severe endometriosis which consistently showed reduced HOXD10 and HOXA5 levels." (PMID 33667269, 2021).
experimental autoimmune encephalomyelitis (1 paper, 2019). An autoimmune demyelinating disease of the central nervous system that is produced experimentally in animals by the injection of homogenized brain or spinal cord in Freund's adjuvant. "Finally, a re-analysis of a recent work performed in mice with experimental autoimmune encephalomyelitis (EAE) shows that widespread CNS inflammation induces a region-specific increased expression of Hoxa5 in SC astrocytes." (PMID 31779094, 2019).
gastric tumor (1 paper, 2014). "HOXA5 was found here to be the most differentially methylated gene between gastric tumor and tumor-adjacent gastric tissue, with the observation of a higher methylation level in tumor replicated in an independent series using a different experimental technique (P < 0.001; pyrosequencing)." (PMID 24674026, 2014).
gliosarcoma (1 paper, 2018). A rare histological variant of glioblastoma (WHO grade IV) characterized by a biphasic tissue pattern with alternating areas displaying glial and mesenchymal differentiation (WHO). "Significantly downregulated transcription factors common to both gliosarcomas were HOXA5, FOXO1, and CEBPA." (PMID 29416795, 2018).
gynecologic cancers (1 paper, 2023). "A relationship between HOXA5 and gynecological cancer has also been reported." (PMID 37834206, 2023).
hemangioma (1 paper, 2021). A benign vascular lesion characterized by the formation of capillary-sized or cavernous vascular channels.
hyperlipidemia (1 paper, 2022). "Building upon these benchmark data, we sought to explore the impact of prolonged hyperlipidemia as well as the effect colchicine-based therapy on a variety of atheroprotective (Klotho, HOXA5, NOTCH1, and OCT4) and proatherogenic (HIF1a, SOX2, BMP4, and NANOG) genes." (PMID 36362692, 2022).
hypothyroidism (1 paper, 2016). Abnormally low levels of thyroid hormone. "Surviving Hoxa5 mutants present hypothyroidism symptoms, including growth retardation and delays in eye opening and ear elevation." (PMID 29615582, 2016). "Despite their transient hypothyroidism phenotype, surviving Hoxa5 homozygous mice are fertile." (PMID 29615582, 2016). "However, growth retardation cannot be attributed exclusively to hypothyroidism as the delayed acquisition of an adult mode of digestion that accompanies the impaired maturation of the digestive tract in Hoxa5 mutants can also contribute to the growth deficit." (PMID 29615582, 2016).
intestinal cancer (1 paper, 2022). "In this paper, the authors reported that HOXA5 inhibited WNT-induced transformation of intestinal cells, counteracted stemness programs, and enforced differentiation in normal tissue and intestinal cancer cells." (PMID 35203377, 2022).
invasive ductal carcinoma (1 paper, 2015). "Previous studies from our laboratory demonstrated that HoxA5 mRNA is expressed in quiescent vessels, but not in angiogenic vessels associated with invasive ductal carcinoma." (PMID 25821967, 2015).
keloid (1 paper, 2021). An irregularly shaped, elevated mark on the skin caused by deposits of excessive amounts of collagen during wound healing. "In this study, we first demonstrated that HOXA5 overexpression in hypertrophic scar-or keloids-derived fibroblasts decreased cell proliferation, migration and collagen synthesis, whereas increased cell apoptosis." (PMID 33414417, 2021). "To investigate the role of HOXA5 in the cell biology of fibroblasts derived from keloids (KFb) or from hypertrophic scars (HSFb), we established HOXA5 overexpression in both types of scar-derived fibroblasts." (PMID 33414417, 2021). "Thus, whether HOXA5 induces apoptosis through alternative pathways in keloids and hypertrophic scars requires further investigation." (PMID 33414417, 2021).
liver cancer (1 paper, 2022). An epithelial or non-epithelial malignant neoplasm that arises from the liver. "Also, referring a HOXA5 ChIP-seq dataset in liver cancer (GSE170384), several peaks were identified in the Slug promoter region." (PMID 36536414, 2022).